NCR1 (natural cytotoxicity triggering receptor 1)
Diseases named in the same sentence as NCR1 in open-access papers (continued):
Sharing a sentence is not in itself a finding about the gene and the disease.
infection (continued). "Taken together, these findings suggest that NCR1 plays an important role in mediating the killing of S. pneumoniae in the lungs during the initial stages of infection." (PMID 21887255, 2011). "In sharp contrast, during the first 6 hours of infection, the bacterial load in the lungs of Ncr1gfp/gfp mice was significantly higher than in Ncr1+/+ and Ncr1+/gfp mice (p<0.01)." (PMID 21887255, 2011). "Thus the vast majority of CD8+/NCR1- lymphocytes recruited during the infection are most probably conventional αβ CD8+ T cells." (PMID 25890354, 2015). "Importantly, the proportion of perforin+ cells within the total NCR1+/CD8+ NK cell population, already higher than in the CD8+/NCR1- T cell population at homeostasis, increased from day 3 of infection." (PMID 25890354, 2015). "As the NCR1+ cell proportion within the lymphocyte population is rather low (5% on average) and the individual variability is high in very young animals, the variations due to infection were less conspicuous for NK cells than for CD8 T lymphocytes." (PMID 25890354, 2015). "We showed the following: (i) NCR1 receptor plays a role in S. pneumoniae induced mortality in mice only when high challenge doses are applied; yet NCR1 plays an imperative role in reducing S. pneumoniae bacterial load in the lungs at early stages after infection." (PMID 21887255, 2011). "This conditioning may occur in the lung prior to infection and could indicate NCR1-mediated pathogen-independent priming of lung macrophages by NK cells." (PMID 21887255, 2011). "In both mice groups, depletion of NK cells 24 h prior to infection resulted in a significant increase of bacterial load 3 h following inoculation compared to the mock-treated mice (3.8 and 2.57 fold increase, p<0.01 and p<0.05 for Ncr1+/+ and Ncr1gfp/gfp, respectively)." (PMID 21887255, 2011). "We see only a slight increase for NCR1+ NK cells in the GNLY-tg mice infected with FN WT, whereas the WT mice infected with FN presented an decreased NK cell amount after infection." (PMID 38215172, 2024). "Nodes 4 and 5 contain immune-related genes, including KLRD1 and NCR1, which regulate natural killer cell activity and surveillance, and CCL28 and CXCR6, which are involved in chemokine signaling and immune cell recruitment to infection sites." (PMID 41114509, 2025). "Within the pre-infection immune cell population, 17.3 ± 1.3% were CD4+ T cells, 21.5 ± 3.1% were CD8+ T cells, 1.8 ± 0.3% were NCR1+ NK cells, 12.8 ± 2.3% were IgM+ B cells, 5.4 ± 0.7% were IgG1+ B cells, 5.9 ± 0.6% were CD14+ monocytes, and 4.9 ± 0.9% of immune cells expressed cell surface CD25." (PMID 39459849, 2024). "Regarding NCR1+/CD3+ NKT cells, both mouse lines showed an increased population after infection." (PMID 38215172, 2024). "Mice lacking the NCR1 (NKp46 in humans) gene died after infection by IV A H1N1 while NK cells were accumulated at the site of infection while NCR1+ mice survived, showing the pivotal role of NKp56 in the eradication of IV infection." (PMID 37749597, 2023). "Nevertheless, we found that Ncr1-specific reconstitution of the IFN-γ gene function was sufficient to confer activation of the myeloid cell compartment upon VACV infection and to control the infection." (PMID 32023327, 2020). "Using NCR1 deficient (NCR1gfp/gfp) mice, we found that the absence of NCR1 led to elevated virus-specific CD8 T cell numbers and accelerated control of the infection." (PMID 30995287, 2019). "There was neither a difference in the density (number of labelled cells per area) nor a change in localization of NCR1+ cells in the infected lambs compared to the controls at any time during the infection." (PMID 25890354, 2015). "We conclude that in small intestinal segments, NCR1+ lymphocytes do not increase in relative numbers, although they most likely increase in absolute numbers during the early stages of infection." (PMID 25890354, 2015).
infection (continued). "Since the expression of CD16 might reflect the cytotoxic potential of NK cells, we analysed the balance between the NCR1+/CD16+ and NCR1+/CD16- subpopulations during the course of infection." (PMID 25890354, 2015). "Interestingly, the function of Ncr1 in the BALB/c background seems to be less important with regard to influenza virus infection and these mice were indeed more sensitive to the infection." (PMID 22615821, 2012). "Since the NCR1 effect was observed 2 hours following F. nucleatum injection we inoculated the HET and KO mice with F. nucleatum and assayed for the presence of various immune cells two hours post infection." (PMID 22457623, 2012). "Therefore, this NCR1-ligandhigh macrophage sub-population could be involved in the conditioning/priming and/or activation of the macrophages by NCR1-expressing NK cells in a cell-to-cell contact interaction prior to infection and during the early phase of infection." (PMID 21887255, 2011). "Therefore we sought to find out if the CD16+ subpopulation displayed a higher perforin content, reflecting a higher cytotoxic potential, but the proportion of perforin+/NCR1+ lymphocytes increased in both CD16- and CD16+ subpopulations (up to 60%) with infection, especially in the jejunum." (PMID 25890354, 2015). "This demonstrates that the absence of NCR1 leads to faster viral control compared to NCR1 expressing WT mice, also without additional transfer of transgenic CD8 T cells upon LCMV docile infection." (PMID 30995287, 2019). "Even though the frequency of mature NK cells (CD27lo CD11bhi) was slightly higher in absence of NCR1, the absolute number of mature NK cells was comparable 2 days after LCMV WE infection." (PMID 30995287, 2019). "The frequency of perforin+ cells increased significantly with infection in the NCR1+ population (in both NCR1+/CD16+ and NCR1+/CD16- populations) but not in the NCR1-/CD8+ population." (PMID 25890354, 2015). "The frequency of NCR1+ cells did not change with infection, while their absolute number slightly increased in the jejunum and the CD8+/NCR1- T cell density increased markedly." (PMID 25890354, 2015). "To evaluate whether the enhanced CD8 T cell response in absence of NCR1 affected the splenic architecture, we analyzed splenic tissue after 8 days of acute LCMV WE infection." (PMID 30995287, 2019). "Properdin, a modulator of the alternative pathway of the complement system, was described to be a ligand for NCR1, but we could not detect increased presence of properdin on CD8 T cells in NCR1gfp/gfp mice 4 days after LCMV WE infection." (PMID 30995287, 2019).
cancer (99 papers, 2011 to 2026). A tumor composed of atypical neoplastic, often pleomorphic cells that invade other tissues. "Data was available for 11,768 individuals in the pan-Cancer cohort, and these showed that high levels of ncr1 expression were associated with an enhanced median survival of 2910 days versus 2089 days, P = 0.017 in individuals with higher levels of XPO1." (PMID 39178254, 2024). "The downregulation of NCR1 on NK cells, a phenotype prevalent in cancer, and its association with impaired cytotoxicity and increased IFNγ production, likely reflects a strategic adaptation to T. gondii infection, prioritizing tissue integrity and control of inflammation over cytotoxic actions." (PMID 40104068, 2025). "Studies have shown that in cancers, the levels of activating receptors (NCR1, NCR2, NCR3) are decreased, and this finding has been linked to poor prognosis." (PMID 38628992, 2024). "To identify which other cancers had a positive association between XPO1, ncr1, and survival, we interrogated the 39 different GDC TCGA datasets covering all the cancer types in the TCGA database." (PMID 39178254, 2024). "HIF-1 affects miR-224, which regulates the signals between NK cells and their receptors (NKp46/NCR1 with a mouse ortholog) and reduces the ability of NK cells to kill cancer cells." (PMID 36787054, 2023). "NCR1 is one of the activating receptors of natural killer cells and has been considered as a target to make the immune system recognize cancer cells." (PMID 35064782, 2022). "Though it has been demonstrated that heparan sulfate, which can be upregulated by cancer cells, can bind to NCR1, the precise identification of the cellular ligands of NCR1 remains a challenge." (PMID 25431955, 2014). "We chose NCR1 expression to evaluate whether cancer cells are expressing for possible NK-mediated cytotoxicity or whether it may be suppressed." (PMID 36671668, 2023). "Blocking NCR1 on NK cells might therefore be a suitable tool to boost T cell responses in chronic viral infections and cancer." (PMID 30995287, 2019). "Natural cytotoxicity triggering receptor 1 (NCR1) activates NK cells and promotes cellular apoptosis in viral-infected, cancer cells and inappropriately activated T cells." (PMID 36911685, 2023). "NK cells effectively inhibit the function of cancer cells through activation of killer cell lectin like receptor K1 (KLRK1) and natural cytotoxicity triggering receptors 1 and 2 (NCR1 and NCR2)." (PMID 33276627, 2020). "CAMKV and MUC2 are the most enriched genes in areas of carcinoma (SSES = 1.37 and SSES = 1.29 respectively), whilst NCR1 (synonym: CD335) and CLEC6A, both selectively expressed in Natural Killer cells (NK-cells), are spatially localised to lymph nodes (SSES = 8.59 and SSES = 6.42 respectively)." (PMID 39003292, 2024). "who observed from circulating leukocytes in healthy and cancer bearing dogs that NCR3, rather than NCR1, was more indicative of the transcriptional signature of canine NK cells." (PMID 40443661, 2025).
bacterial infection (3 papers, 2014 to 2022). "In addition, we and others have shown that NCR1 may be central to the recognition and eradication of certain viral and bacterial infections." (PMID 25431955, 2014).
neurodegenerative disease (2 papers, 2012 to 2020). A disorder of the central nervous system characterized by gradual and progressive loss of neural tissue and neurologic function. "In any case, our results argue for NCR1 as a potential CNS tissue marker of neurodegenerative disease." (PMID 22212381, 2012).
NCR1 also shares sentences with these, for which no sentence is quoted: cervical carcinoma (12 papers); pancreatic cancer (10); endometriosis (7); myeloma (7); glioblastoma (6); HCMV infection (6); gastric cancer (5); hepatoma (5); autoimmune disease (4); graft versus host disease (4); metastatic melanoma (4); Miscarriage (4); prostate tumors (4); renal cell carcinoma (4); adenocarcinoma (3); celiac disease (3); Chronic colitis (3); eosinophilia (3); H1N1 influenza (3); Hepatitis (3); HIV-1 infection (3); inflammation (3); liver cirrhosis (3); metastatic prostate carcinoma (3); metastatic tumors (3); multiple myeloma (3); myelodysplastic syndrome (3); preeclampsia (3); Salmonella Infections (3); acute lymphoblastic leukemia (2).
A further 112 diseases each share a sentence with NCR1 in 2 papers or fewer.